MIR5707 (microRNA 5707)
Synonyms: hsa-mir-5707
Gene: MicroRNA gene on chromosome 7 (158,591,616 to 158,591,696, forward strand). Ensembl gene ENSG00000265598.
Homologues: Orthologues: chimpanzee MIR5707 (100% identical).